TTTY3 (testis expressed transcript, Y-linked 3)
Synonyms: TTY3; TTTY3A; LINC00121; NCRNA00121
Gene: Long non-coding RNA gene on chromosome Y (25,728,490 to 25,733,388, forward strand). Ensembl gene ENSG00000231141.
Homologues: Paralogues in human: TTTY3B (100% identical).